GPR34 (G protein-coupled receptor 34)
Description:
G protein-coupled receptor of lysophosphatidylserine (LysoPS) that plays different roles in immune response. Acts a damage-sensing receptor that triggers tissue repair upon recognition of dying neutrophils (By similarity). Mechanistically, apoptotic neutrophils release lysophosphatydilserine that are recognized by type 3 innate lymphoid cells (ILC3s) via GPR34, which activates downstream PI3K-AKT and RAS-ERK signaling pathways leading to STAT3 activation and IL-22 production (By similarity). Plays an important role in microglial function, controlling morphology and phagocytosis (By similarity).
Synonyms: LPS1; LYPSR1
Tractability: Small molecule: a structure with a bound ligand is known; a high-quality ligand is known; it belongs to a druggable protein family. Antibody: UniProt places it where antibodies can reach, with high confidence; its Gene Ontology location is reachable by antibodies, with high confidence; UniProt predicts a signal peptide or a membrane-spanning region. PROTAC: a small molecule that binds it is known.
Target class: Family A G protein-coupled receptor; Membrane receptor
Gene: Protein-coding gene on chromosome X (41,688,973 to 41,698,371, forward strand). Ensembl gene ENSG00000171659.
Subcellular location: Cell membrane
Subcellular location (Human Protein Atlas): Cytosol
Gene Ontology:
Molecular function: protein binding; G protein-coupled purinergic nucleotide receptor activity; G protein-coupled receptor activity
Biological process: G protein-coupled receptor signaling pathway; G protein-coupled purinergic nucleotide receptor signaling pathway
Cellular component: plasma membrane; membrane
Homologues: Orthologues: macaque GPR34 (99% identical), mouse Gpr34 (90% identical), pig GPR34 (90% identical), rabbit GPR34 (89% identical), rat Gpr34 (88% identical), tropical clawed frog gpr34 (50% identical), zebrafish gpr34b (35% identical). Paralogues in human: P2RY14 (26% identical), P2RY12 (23% identical), GPR87 (23% identical), P2RY13 (22% identical), PTAFR (21% identical), GPR171 (21% identical).
Diseases named in the same sentence as GPR34 in open-access papers:
GPR34 is named in the same sentence as 33 diseases in open-access papers, as found by Europe PMC text mining. Sharing a sentence is not in itself a finding about the gene and the disease. The quoted sentences say what the papers report.
MALT lymphoma (6 papers, 2021 to 2025). An indolent, extranodal type of non-Hodgkin lymphoma composed of small B-lymphocytes (centrocyte-like cells). "Alternatively, TBL1XR1 and GPR34 mutations are frequent in salivary gland MALT lymphomas (24% and 19%) and uncommon in other MALT lymphomas." (PMID 38977312, 2024). "GPR34 translocations and mutations are associated with salivary gland MALT lymphoma specificity." (PMID 40689396, 2025). "Furthermore, t(X;14)(p11.4;q32) which cause GPR34 over-expression is also restricted to MALT lymphoma of salivary gland, such as MALT lymphomas with GPR34 mutation." (PMID 35008340, 2021). "This identified recurrent novel mutations in several genes encoding G-protein coupled receptor (GPCR), including GPR34 and CCR6, and lead to the discovery of a significant association between GPR34 and TBL1XR1 mutations in salivary gland MALT lymphoma." (PMID 34021249, 2021). "Growing studies determine that the upregulation of GPR34 is implicated in the onset and progression of various cancers, including triple negative breast cancer (TNBC), cervical cancer, colorectal cancer (CRC), MALT lymphoma, gastric cancer, glioma, and BCR/ABL-positive leukemia." (PMID 40862294, 2025). "Interestingly, distinct mutation profiles, corresponding to clusters of nonsense and frameshift mutations in the C-termini of GPCRs, GPR34, CCR6, and CCR4, have been reported in mucosa-associated lymphoid tissue (MALT) lymphoma and adult T cell leukemia/lymphoma (ATLL) as gain-of-function mutations." (PMID 34852802, 2021).
cervical cancer (4 papers, 2021 to 2025). A primary or metastatic malignant neoplasm involving the cervix. "GPR34, considered as orphan receptors, has been demonstrated as a crucial cancer driver in various cancers, including cervical cancer, gastric cancer, and glioma." (PMID 40862294, 2025). "The results are thus conclusive that miR-300 functionally targets GPR34 in cervical cancer to exert its tumor-suppressive role." (PMID 34950207, 2021). "The qRT-PCR showed that cervical cancer tissues possess significantly (P < 0.05) higher transcript levels of GPR34 than the normal matched cervical tissues." (PMID 34950207, 2021). "The immunohistochemical staining analysis of GPR34 from paired cancer and normal tissues from four cervical cancer patients also confirmed the upregulation of GPR34 in cervical cancer tissues." (PMID 34950207, 2021). "MTT assay showed that GPR34 downregulation in cervical cancer cells led to significant (P < 0.05) decrease in their in vitro proliferation rate at indicated culture intervals." (PMID 34950207, 2021). "More support was gained from the expression analysis of GPR34 from cervical cancer and normal matched tissues." (PMID 34950207, 2021). "Collectively, the results of the current study are indicative of the tumor-suppressive regulatory role of miR-300 in cervical cancer and suggestive of the potential therapeutic value of miR-300/GPR34 molecular axis." (PMID 34950207, 2021). "Against this backdrop, the present study was designed to decipher the role of miR-300 in cervical cancer via modulation of G protein-coupled receptor 34 (GPR34) expression." (PMID 34950207, 2021). "The findings of the present are suggestive of the therapeutic potential of miR-300/GPR34 axis in the management of cervical cancer." (PMID 34950207, 2021). "G protein-coupled receptor 34 (GPR34) was found to be the functional regulatory target of miR-300 in cervical cancer." (PMID 34950207, 2021). "The results of miR-300 interaction and expression analysis of GPR34 are indicative of posttranscriptional targeting of miR-300 in cervical cancer." (PMID 34950207, 2021). "GPR34 was found to be significantly (P < 0.05) overexpressed in cervical cancer tissues and cell lines." (PMID 34950207, 2021). "At the molecular level, miR-300 was shown to target GPR34 at the posttranscriptional level to exert its tumor-suppressive effects on cervical cancer cells." (PMID 34950207, 2021). "As expected, the transcript levels of GPR34 were significantly (P < 0.05) higher in all the cervical cancer cell lines (CaSki, HeLa, HT-3, and ME-180) in comparison to the HcerEpic cervical epithelial cells." (PMID 34950207, 2021). "Several studies have addressed elevated expression levels of GPR34 in malignancies, including cervical cancer, metastatic melanoma, MALT lymphoma, BCR/ABL-positive leukemia, gastric cancer, and colon cancer, as well as its essential roles in tumor development and progression." (PMID 34997428, 2022). "Silencing of GPR34 inhibited the growth of the cervical cancer cells." (PMID 34950207, 2021). "However, overexpression of GPR34 could prevent the tumor-suppressive effects of miR-300 on cervical cancer cells." (PMID 34950207, 2021). "GPR34 upregulation has been detected in various tumor tissues, including melanoma, human MZL cells, leukemia, stomach, and cervical cancer." (PMID 34997428, 2022).
gastric cancer (4 papers, 2021 to 2025). A primary or metastatic malignant neoplasm involving the stomach. "ABHD16A, as an emerging phosphatidylserine-specific lipase, involves in lipid metabolism leading to lysophosphatidylserines (lyso-PSs) accumulation, which stimulates RhoA and downstream LIMK/cofilin cascade activity through GPR34/Gi subunit, thus causes metastasis of gastric cancer." (PMID 33875796, 2021). "Reportedly, knocking down GPR34 expression can inhibit the proliferation and migration of gastric cancer cells, and GPR34 regulates metabolism and metastasis in gastric cancer." (PMID 38007443, 2023). "In gastric cancer cells, GPR34 knockdown downregulated not only the expression of p-PI3KR1 in NCI-N87 cells, but also the expression of PI3KCD (p110δ) in HGC-27 cells." (PMID 34997428, 2022). "We have previously shown that GPR34 is involved in the proliferation of gastric cancer and leukemic cells through PI3K/AKT and/or ERK pathways." (PMID 34997428, 2022). "Our previous studies have demonstrated that increased expression of GPR34 was involved in the proliferation of gastric cancer HGC-27 cells via the PI3K/AKT pathway." (PMID 34997428, 2022). "The elevated lyso-PS contributed to activation of RhoA through GPR34/Gi, thus resulting in gastric cancer metastasis." (PMID 33875796, 2021). "Combined with previous data from gastric cancer and leukemic cells, our present data from LS174T cells indicates the need for additional, related assays to confirm the complex roles and underlying mechanism of GPR34 in the progression and development of colorectal cancer and other cancers." (PMID 34997428, 2022). "We have previously shown that GPR34/PI3K/AKT and GPR34/PI3K/ERK play important roles in proliferation, apoptosis, and migration in gastric cancer and BCR/ABL-positive leukemia." (PMID 34997428, 2022).
glioma (4 papers, 2019 to 2025). A benign or malignant brain and spinal cord tumor that arises from glial cells (astrocytes, oligodendrocytes, ependymal cells). "(c) Graph shows the log-fold change expression of SGmic genes (P2ry13, P2ry12, Gpr34, Slc2a5, Siglec-H, Olfml3, Tmem119, Fcrls) in glioma-associated microglia isolated from GL261 tumors as compared to microglia isolated from healthy control brains." (PMID 30764877, 2019). "(b) The log-fold change expression of SGmic genes (P2ry13, P2ry12, Gpr34, Slc2a5, Siglec-H, Olfml3, Tmem119, Fcrls) in glioma-associated microglia isolated from RCAS tumors compared to microglia isolated from healthy control brains is shown." (PMID 30764877, 2019). "(a) The log-fold change expression of SGmic genes (P2ry13, P2ry12, Gpr34, Slc2a5, Siglec-H, Olfml3, Tmem119, Fcrls) in glioma-associated microglia isolated from experimental RCAS tumors compared to microglia isolated from healthy control brains is shown." (PMID 30764877, 2019). "It is only known that the stimulation of GPR34 enhances the malignancy and carcinogenesis of glioma by promoting an epithelial-mesenchymal transition, G1/S phase cell cycle transition, and TGF-beta/Smad signaling." (PMID 39963421, 2024). "Research has found that a subset of microglia that have engulfed glioma-derived extracellular vesicles show significant downregulation of genes involved in sensing tumor cells, tumor danger signals, and tumor-killing, such as SIGLEC-H and the GPR34 (G protein-coupled receptor 34)." (PMID 38523155, 2024).
hepatocellular carcinoma (4 papers, 2020 to 2022). A malignant tumor that arises from hepatocytes. "Expression of GPR34 in hepatocellular carcinoma and that of GPR55 in breast cancer have been reported to be positively correlated with the prognosis." (PMID 35315587, 2022). "Three maker genes were found in liver carcinoma of HPA database (TREM2 and GPR34 from macrophage, PDCD1 from Treg cell), which indicated that macrophages and Treg cells existed in liver carcinoma." (PMID 36221095, 2022).
lymphoma (4 papers, 2017 to 2024). A malignant (clonal) proliferation of B- lymphocytes or T- lymphocytes which involves the lymph nodes, bone marrow and/or extranodal sites. "Overexpression of GPR34 in lymphoma resulted in phosphorylation of ERK, induced NF-κB-mediated gene transcription, and increased cell proliferation." (PMID 34997428, 2022). "Overexpression of GPR34 in lymphoma and HeLa cells results in phosphorylation of ERK, PKC, and CREB; induces CRE, AP1, and NF-κB-mediated gene transcription; and increases cell proliferation." (PMID 34997428, 2022). "The overexpression of GPR34 in lymphoma results in the phosphorylation of ERK, PKC, and CREB and increased cell proliferation." (PMID 32283838, 2020). "In an effort to model human lymphoma, we generated B cell–specific GPR34 GOF knock-in (KI) mice." (PMID 39412501, 2024).
colorectal cancer (3 papers, 2021 to 2022). A primary or metastatic malignant neoplasm that affects the colon or rectum. "This required us to perform a more in-depth investigation of the underlying mechanisms of GPR34/PI3K in colorectal cancer cell proliferation." (PMID 34997428, 2022). "Previous studies have revealed that lyso-PS stimulates the chemotactic migration of human glioma cell U87 or colorectal cancer cells through the GPR34 and PI3K/Akt pathways, suggesting that lyso-PS is associated with tumor invasion and metastasis." (PMID 33875796, 2021). "However, the mechanisms underlying how GPR34 functions to regulate growth and proliferation of colorectal cancer cells remains to be clarified." (PMID 34997428, 2022). "For example, lyso-PS can provoke eosinophil degranulation via P2Y10, suppress IL-2 production by activated T cells via GPR174, and stimulate chemotactic migration and invasion of colorectal cancer cells via GPR34." (PMID 33875796, 2021). "In order to further determine the effects of GPR34 on the growth and proliferation of LS174T cells, exogenous LysoPS (optimized, 20 μM) proved as a stimulation for the migration of colorectal cancer cells through GPR34 and PI3K/Akt pathway, was added into the complete DMEM media." (PMID 34997428, 2022).
breast carcinoma (2 papers, 2022 to 2023). "Of note, the expression of GPR34 was significantly higher in TNBC tissues compared to that in other breast cancer (non-TNBC) tissues, indicating that GPR34 plays a crucial role in the onset and progression of TNBC." (PMID 38007443, 2023).
thyroid cancer (2 papers, 2021 to 2025). "The survival analysis showed that high GPR34 expression was positively correlated with improved survival in thyroid cancer patients." (PMID 40862294, 2025).
Alzheimer disease (1 paper, 2026). A progressive, neurodegenerative disease characterized by loss of function and death of nerve cells in several areas of the brain leading to loss of cognitive function such as memory and language. "While GPR34 deficiency has been linked to impaired microglial phagocytosis, its regulation in relation to amyloid-β (Aβ) and tau pathology in Alzheimer's disease (AD) remains unclear." (PMID 42295430, 2026).
anaplastic thyroid carcinoma (1 paper, 2025). "G protein-coupled receptor 34 (GPR34) is an orphan receptor within the G protein-coupled receptor (GPCR) superfamily, and its specific role in anaplastic thyroid carcinoma (ATC) remains to be elucidated." (PMID 40862294, 2025).
cardiomyopathy (1 paper, 2023). A disease of the heart muscle or myocardium proper. "Furthermore, the ablation of Gpr34 suppressed necrosis in cardiomyocytes and prevented the development of pressure overload-induced cardiomyopathy." (PMID 37524709, 2023).
colon cancer (1 paper, 2022). "Furthermore, we showed that GPR34 knockdown inhibited the proliferation of LS174T colon cancer cells and related xenograft tumor growth." (PMID 34997428, 2022). "It has previously shown that GPR34 is upregulated in colon cancer tissues and cell lines." (PMID 34997428, 2022). "It was reported that GPR34 was upregulated in colon cancer cell lines and tissues, and might act as a potential proto-oncogene involved in the development and progression of colon cancer." (PMID 34997428, 2022).
Cryptococcus neoformans infection (1 paper, 2021). "The first LysoPS receptor to be deorphanized was GPR34, an X-linked GPCR that is most abundantly expressed in microglia, capable of coupling to Gαi-containing heterotrimers, and protective in the central nervous system (CNS) against Cryptococcus neoformans infection-induced pathology." (PMID 34815397, 2021).
glioblastoma (1 paper, 2020). The most malignant astrocytic tumor (WHO grade IV). "Another microglial receptor that is capable of sensing lysophosphatidylserine exposed on glioblastoma cells is GPR34." (PMID 32299465, 2020). "Similar to Siglech, Gpr34 a gene known to directly sense ligands expressed in glioblastoma cells is downregulated in EV-GFPpos microglia compared to GFPneg and control microglia (log2 fold-change − 1.96 and − 2.37, respectively)." (PMID 32299465, 2020).
HCMV infection (1 paper, 2017). "Network analysis of the differentially expressed genes in cord DCs, revealed among the downregulated genes after 16 h of HCMV infection several GPCRs with pro-inflammatory response function (ADORA3, ARRB1, C5AR1, CXCR4, GPR34, GPR183, GRK3, and RGS18)." (PMID 28993767, 2017).
heart failure (1 paper, 2023). Inability of the heart to pump blood at an adequate rate to meet tissue metabolic requirements. "Thus, iPLA2β, as well as GPR34, may constitute therapeutic targets for patients with heart failure." (PMID 37524709, 2023).
injury (1 paper, 2019). Damage inflicted on the body as the direct or indirect result of an external force, with or without disruption of structural continuity. "Our previous gene screening study using a mouse model of motor nerve injury showed that the G-protein-coupled receptor 34 gene (GPR34) is induced by nerve injury." (PMID 30975169, 2019).
lymphoplasmacytic lymphoma (1 paper, 2024). A clonal neoplasm of small B-lymphocytes, lymphoplasmacytoid cells, and plasma cells involving the bone marrow, lymph nodes, and the spleen. "While GPR34 translocations and GOF mutations are enriched in SG cases, GPR34 expression is generally increased in MALT, MZB, and lymphoplasmacytic lymphomas, suggesting a broader pathological relevance of the receptor." (PMID 39412501, 2024).